IGF1 (insulin like growth factor 1)
Diseases named in the same sentence as IGF1 in open-access papers (continued):
Sharing a sentence is not in itself a finding about the gene and the disease.
osteoporosis (continued). "Although potential markers of osteoporosis in diabetic women have been previously proposed, here we propose IGF-1 and sclerostin as potential markers as well." (PMID 34690653, 2021). "IGF-1 supports osteoblast differentiation, with decreasing levels of IGF-1 in the aging population being associated with osteoporosis." (PMID 33424724, 2020). "It is interesting to note that with osteoporosis, there is a decrease in IGF-1 and its binding proteins in the serum." (PMID 32157596, 2020). "Studies32,33 have shown level of IGF-1 in postmenopausal patients with osteoporosis decreased significantly, and IGF-1 was positively correlated with BMD and E2." (PMID 32267378, 2020). "Osteoporosis patients have low level of IGF-1 and high level of ET-1, and IGF-1 and ET-1 are closely related to cytokines and bone mineral density." (PMID 31258577, 2019). "Regarding the biochemical parameters, the osteoporosis group had significantly lower levels of total bilirubin, PT-INR, IGF-1, and BCAAs than the non-osteoporosis group." (PMID 31878909, 2019). "The innovation of this study was to explore relationships of IGF-1, ET-1 with serum cytokines and bone mineral density in patients with osteoporosis." (PMID 31258577, 2019). "As a growth factor with good application prospects, the signal pathway for IGF1 action can be used in the treatment of osteoporosis and osteopenia, Future studies should observe the molecular mechanism of its influence on osteogenesis regulation." (PMID 31419079, 2019). "Considering the vitally functional significance of the IGF-1, variations in the IGF-1 gene are possible susceptibility candidate loci for osteoporosis." (PMID 29747606, 2018). "In patients with osteoporosis, primary osteoblasts have an impaired IGF-1R signaling decoupled from IGF-1 stimulation, which causes lower proliferation rate and differentiation and therefore bone loss." (PMID 29138637, 2017). "Of note, the IGF-1 replacement in animals with cholestatic disease is able to mitigate and partially reverse osteoporosis." (PMID 27840821, 2016). "GH and IGF-1 have a great effect on bone resorption and bone anabolism and their administration has a positive effect on osteoporosis and fracture healing." (PMID 25147565, 2014). "Clinical studies reporting the use of GH and IGF-1 in osteoporosis and fracture healing are outlined." (PMID 25147565, 2014). "Although the role of IGF-1 in antler growth has been disputed, the presence IGF-1 within VAM-B makes this product a potential therapeutic agent worth future development for managing osteoporosis." (PMID 22951396, 2012). "Similarly, Bacillus amyloliquefaciens demonstrates anti-osteoporosis effects mediated by the increased IGF-1 levels." (PMID 40667443, 2025). "This reduction in IGF-1 contributes to the onset of osteoporosis in diabetic patients." (PMID 40722438, 2025). "IGF-1 might be involved in as a myokine linking muscle to bone in hyponatremia-induced osteoporosis in mice." (PMID 40227313, 2025). "This beneficial effect of LF is attenuated when interfering with IGF1 using small interfering RNA (siRNA), implying that LF’s actions in treating aging-related osteoporosis may be mediated through the IGF1 pathway." (PMID 39066929, 2024). "Estrogen and IGF-1 decrease with age, mediating the activation of osteoclast cytokines, subsequently promoting bone resorption, ultimately leading to osteoporosis, and by mediating elevated catabolic cytokine levels, promoting decreased muscle mass and strength, ultimately leading to frailty." (PMID 38982542, 2024). "The study findings suggest that IGF-1 may serve as a valuable tool for evaluating and predicting osteoporosis in survivors of childhood acute leukemia." (PMID 38610974, 2024). "IGF-1, which reaches its peak during puberty, a critical period for acquiring peak bone mass, has been extensively studied in relation to bone strength and, consequently, osteoporosis." (PMID 38260127, 2023).
osteoporosis (continued). "Low IGF-1 level was common among thalassemia patients with osteoporosis (54.9%)." (PMID 37251676, 2023). "While analyzing data from the FinnGen consortium, the OR value of IGF-1 failed to reach a significant association between IGF-1 and osteoporosis with all p value above 0.05." (PMID 38260127, 2023). "The accumulation of IR and TG, chronic inflammatory processes, vitamin D deficiency, and insulin-like growth factor-1 (IGF-1) reduction play important roles in the pathogenesis of NAFLD, which may be related to osteoporosis." (PMID 38041076, 2023). "measured serum IGF-1 concentration in 107 healthy females and 116 females with osteoporosis." (PMID 36967758, 2023). "We found that the IGF-1 level was associated with osteoporosis, however, the association did not attain statistical significance in a multivariate analysis." (PMID 37775530, 2023). "Furthermore, logistic regression analysis showed that participants with IGF-1 ≤ 82.00 ng/mL had an OR of 2.275 (95% CI 0.993–5.324; p = 0.052) for LS adjusted by osteoporosis, osteoarthritis, and the propensity score estimated from sex, age, and BMI." (PMID 35948948, 2022). "IL6, CXCR4, IGF1, and PLOD2 played crucial roles in weightlessness osteoporosis, which provided a theoretical basis for the pathogenic mechanism and treatment of weightlessness osteoporosis." (PMID 35479581, 2022). "The results of the univariate regression analysis showed that the IGF-1 level (OR = 0.976, 95% confidence interval [CI] = 0.958–0.994; p = 0.0308) and osteoporosis status (OR = 2.423, 95% CI = 1.060–5.537; p = 0.02086) were significantly associated with a “decline in masticatory function”." (PMID 36078393, 2022). "Other studies suggest that low concentrations of insulin and insulin-like growth factor 1 (IGF-1) may affect osteogenic activity and lead to osteoporosis." (PMID 35082963, 2022). "Meanwhile, many relevant biomarkers have shown the correlation between osteoporosis and already been used to auxiliary diagnose OP and assess bone metabolism, such as leptin, Interleukin-6 (IL-6), insulin-like growth factor 1 (IGF-1), and vascular endothelial growth factor (VEGF)." (PMID 35993023, 2022). "Multiple linear regression analysis was performed with the factors, and age (β = 0.266, p = 0.001), IGF-1 (β = − 0.164, p = 0.033), osteoporosis (β = − 0.273, p = 0.001), and osteoarthritis (β = − 0.302, p < 0.001) were found to be significantly associated with the Locomo-25 score." (PMID 35948948, 2022). "It is currently believed that glucocorticoids can lead to osteoporosis by promoting the differentiation and maturation of osteoclasts, inhibiting the generation of osteoblasts, and decreasing the production of insulin-like growth factor 1, growth hormones, etc.." (PMID 36033513, 2022). "Measured in serum, miR-26a could serve as a prognostic marker for osteoporosis and appears to regulate serum IGF1 levels in osteoporosis patients." (PMID 36289702, 2022). "Moreover, intragastric intervention with LF increased IGF1 mRNA expression and promoted bone formation in a senile osteoporosis mouse model." (PMID 35267914, 2022). "The downregulation of IGF-1/PI3K/Akt activity that occurs in osteoporosis may lead to muscle atrophy." (PMID 36237187, 2022). "In particular, mTORC1 has emerged as a common effector mediating the bone anabolic effect of IGF1, WNTs, and BMPs; thus, a dysregulation of mTORC1 could contribute to various skeletal diseases including osteoarthritis and osteoporosis." (PMID 34299021, 2021). "The results may be related to increase NO production, reduced stimulation of hormones and insulin-like growth factor-1, and excessive muscle breakdown, which may be responsible for the development of osteoporosis." (PMID 32670052, 2020).
osteoporosis (continued). "In bone, the growth hormone/IGF-1 axis stimulates growth directly by activating chondrocyte proliferation and osteoblast differentiation, while the reduction of IGF-1 serum levels and insulin-deficiency of type 1 diabetes were associated with osteoporosis." (PMID 32668736, 2020). "The present study also showed that low IGF-1 levels were associated with osteoporosis, although there was no statistical significance in the multivariate analysis." (PMID 31878909, 2019). "Patients with osteoporosis have decreased level of IGF-1 but increased level of ET-1, and they are closely related to cytokines and bone mineral density and may participate in the pathogenesis of osteoporosis." (PMID 31258577, 2019). "In fact, higher protein diets may actually protect against osteoporosis, in part, as a result of the increased hepatic release of insulin-like growth factor 1 (IGF-1)." (PMID 31121843, 2019). "In this specific disease, insulin-like growth factor 1 (IGF-1) polymorphisms seem to have a higher influence on bone loss than the collagen type Iα1 Sp1 polymorphism, which was previously evaluated in primary osteoporosis." (PMID 27840821, 2016). "But there are few evidences on the role of genetic variation of IGF-1 on the BMD or osteoporosis." (PMID 24639846, 2014). "Besides PTH, there are also some other potential anabolic agents for osteoporosis treatment, including parathyroid hormone related protein (PTHrP), growth hormone, insulin-like growth factor-1 (IGF-1), and so on." (PMID 24516619, 2014). "Therefore, we conducted a study to observe the relationship between three common SNPs of IGF-1, rs35767, rs2288377 and rs5742612, and osteoporosis and BMD in the postmenopausal female population in our study." (PMID 24639846, 2014). "The aim of the present review is to evaluate the clinical studies published in the literature on the effect of GH and IGF-1 on bone metabolism in human subjects affected by severe osteoporosis and bone healing after surgery in non-GH deficient subjects." (PMID 25147565, 2014). "Moreover, GHT might be considered an additive treatment for osteoporosis in childhood cancer survivors with low IGF-1 levels." (PMID 38610974, 2024). "Therefore, GHT could be considered a potential additive treatment for osteoporosis in childhood cancer survivors with low IGF-1 levels." (PMID 38610974, 2024). "Thus, decreased IGF-1 levels have been observed in both male and female patients with osteoporosis." (PMID 36967758, 2023). "Essentially, our results suggest that IGF system members, particularly IGF-1, may serve as potential predictive markers during early growth stages and represent promising therapeutic candidates for addressing osteoporosis in validated regional individuals." (PMID 38260127, 2023). "Skeletal muscle secretes various myokines (e.g., myostatin, IL6, IGF-1, irisin) in an autocrine, paracrine, or endocrine manner to regulate the metabolic activities of bone cells in various ways and ultimately contribute to the pathogenesis of osteoporosis mechanisms." (PMID 36578964, 2022). "Moreover, being 70–79 years of age (IRR = 3.89; 95% CI 1.61–9.44), being 80 years of age or older (IRR = 8.07; 95% CI 3.05–21.36), having osteoporosis (IRR = 1.76; 95% CI 1.02–3.03) and having low IGF-1 (IRR = 1.76; 95% CI 1.02–3.04) were also risk factors for the incidence of dynapenia." (PMID 36109388, 2022). "Individuals with T2DM are often at risk for decreased bone density, making it essential to understand the relationship between IGF-1 and BMD for effective prevention and treatment of osteoporosis." (PMID 39398331, 2024). "Decreased IGF-1 have been reported in both patients with osteoporosis and NAFLD, indicating the important role of IGF-1 in the liver-bone axis." (PMID 38524631, 2024).
osteoporosis (continued). "After screening the core therapeutic ingredients, a PPI network was constructed to determine core targets; our results showed that AKT1, CASP3, EGFR, ESR1, IGF1, MAPK1, and MAPK14 are important for AB–DA treatment of osteoporosis." (PMID 37849727, 2023). "In our own findings, we observed that a higher circulating level of IGF-1 is associated with a decreased risk of osteoporosis (OR = 0.998, 95% CI = 0.997–1.000, P = 0.032), in line with previous research indicating that elevated IGF-1 levels may serve as a protective factor against osteoporosis." (PMID 38260127, 2023). "Additionally, an article focusing on PBC and osteoporosis highlighted the strong connection between the two and analyzed various factors that may impact bone metabolism in PBC patients, such as vitamin deficiencies, IGF-1, BMP, bile acids, and bilirubin." (PMID 38162659, 2023). "Microenvironmental agents for the improvement of MSC function in osteoporosis have also been reported to include the gasotransmitter H2S donor GYY4317 and Insulin-like growth factor 1 (IGF1), together with its binding protein (IGFBP3)." (PMID 36968100, 2023). "Among them, IL6, CXCR4, IGF1, and PLOD2 were finally included in this study for follow-up analysis, because the relationships between these genes and weightlessness osteoporosis remained unclear, which was worth further analyzing." (PMID 35479581, 2022). "The circulating level of IGF-1 was found to be an independent predictor of total BMC in healthy elderly women and was significantly lower in men and women with osteoporosis." (PMID 25147565, 2014). "A threshold concentration of circulating IGF-1 is necessary for normal bone growth and IGF-1, IGFBP-3, and ALS play a prominent role in the pathophysiology of osteoporosis." (PMID 25147565, 2014). "In elderly women, serum IGF-1 concentration was found to be an independent predictor of total BMC and low levels of IGF-1 have been reported in both males and females with osteoporosis." (PMID 25147565, 2014). "In conclusion, the presence of estrogen, testosterone, and IGF-1 and enriched protein contents within VAM-B makes this product a potential therapeutic agent worth future development for managing osteoporosis in women." (PMID 22951396, 2012). "Additional studies are needed to confirm the potential mediation of IGF-1 levels in the links between OC use and adverse health outcomes, such as CVD and osteoporosis." (PMID 21599947, 2011). "In line with this, we found that IGF1 levels in bone (where miR-122 is not expressed) were unchanged, consistent with the decreased incidence of osteoporosis in female Myc heterozygotes, despite decreased circulating IGF1." (PMID 37908640, 2023). "Patients with chronic liver disease complicated by osteoporosis exhibited reduced serum levels of IGF-1 compared with those without osteoporosis." (PMID 37511813, 2023). "Not surprisingly, the administration of GH or IGF-1 for treating osteoporosis in clinical trials has yielded mixed results." (PMID 35665221, 2022). "Patients with CLD complicated by osteoporosis were reported to have lower serum IGF-1 levels than those without osteoporosis." (PMID 36010307, 2022). "For example, in postmenopausal women with osteoporosis, serum IGF-1 does not differ from that in postmenopausal women without osteoporosis." (PMID 35665221, 2022). "INS, BGLAP, PTH, IGF1, and TNF were the top 5 most studied genes between osteoporosis and DM." (PMID 35719662, 2022). "IGF-1 levels are lower in cirrhotic patients with osteoporosis when compared to those without osteoporosis, and they are also associated with the degree of hepatic insufficiency." (PMID 27840821, 2016). "Previous studies demonstrated that a low dose IGF-1 treatment increased blood markers for bone formation without increased for resorption markers in osteoporosis of postmenopausal women and a dose response effect was described." (PMID 25147565, 2014).
osteoporosis (continued). "In this study, the up-regulation of miR-422a may reduce the production and secretion of IGF1 in circulating monocytes, leading to low BMD and osteoporosis in postmenopausal women." (PMID 24820117, 2014). "However, localized administration of 4 μg of IGF-1 did not promote osseointegration two weeks post-surgery in either healthy rabbits or those with osteoporosis." (PMID 39859058, 2025). "In the FinnGen dataset, IGF-1 and IGFBP-3 were not identified to be associated with osteoporosis." (PMID 38260127, 2023). "Additional studies are needed to delineate the role of IGF-1 vs. IGF-2 and to determine how IGFBPs may be temporally and differentially regulated during osteoporosis, psychological stress, and in osteoporotic patients who have a history of mental health disorders." (PMID 31024360, 2019). "Although proinflammatory cytokines are known to promote bone loss directly, they also lead to altered sensitivity and secretion of growth hormone (GH) and insulin-like growth factor-1 (IGF-1) in IBD, which may be another critical mechanism leading to osteoporosis." (PMID 29343614, 2018). "A large body of literature have also reported that IGF-1 and several IGF-binding proteins (IGFBPs), like IGFBP-1, 3, 4, and 5, were positively correlated with bone mass and could serve as independent predictors for the occurrence of osteoporosis and fracture." (PMID 29747606, 2018). "Whilst administration of IGF-1 to osteoporosis patients has little positive effect on bone density, osteoblasts isolated from osteoporotic donors have an attenuated PI3K/AKT response to IGF-1, suggesting that IGF-1R responsiveness may play a role in osteoporosis." (PMID 22833734, 2012). "Myc heterozygous mice have decreased serum IGF1 levels, are long-lived, and are resistant to the development of osteoporosis, thus presenting a unique model system to address whether reducing IGF1 signaling can increase lifespan without deleterious effects on health span." (PMID 37908640, 2023). "Short stature and osteoporosis are common in Duchenne muscular dystrophy (DMD) and its pathophysiology may include an abnormality of the growth hormone/insulin-like growth factor-1 (GH/IGF-1) axis, which is further exacerbated by long-term glucocorticoid (GC) treatment." (PMID 35191394, 2022). "The sample sizes for four gene loci, namely, COL1A1 1245GT (rs1800012), IGF1 (rs5742612), IL6 G174C (rs1800795), and ESR1 XbaI (rs9340799), were sufficient for a conclusion of noncorrelation with osteoporosis." (PMID 35452412, 2022).